INS (insulin)
Diseases named in the same sentence as INS in open-access papers (continued):
Sharing a sentence is not in itself a finding about the gene and the disease.
Obesity (continued). "In 2013, in a European prospective analysis, authors evaluated the associations between self-reported DM, its duration, age at DM diagnosis, and insulin treatment with the risk of BTC and HCC, independent of obesity." (PMID 39410050, 2024). "Between-group comparisons demonstrated significant differences between the groups in terms of obesity indices (body weight, BMI, and body fat), lipid profiles (TG, TC, LDL-C, and HDL-C), FBS and insulin levels, HOMA-IR, and HOMA-B at the end of the study (P < 0.05)." (PMID 39080737, 2024). "In mice with diet-induced obesity, the overexpression of IGFBP-1 improved insulin sensitivity." (PMID 38928106, 2024). "Clearance of p16INK4a senescent cells in the pancreas improved glucose metabolism and insulin secretion, and clearance of p21CIP1 cells from VAT was shown to improve adipogenesis and insulin sensitivity and decrease VAT volume and macrophage infiltration in murine obesity models." (PMID 39063184, 2024). "Obesity and hyperlipidemia exert a negative impact on insulin sensitivity, significantly impairing glucose transport through insulin-dependent tissues such as skeletal muscle, adipose tissue, and the liver." (PMID 39595646, 2024). "Intraperitoneal injection of SCD-targeted antisense oligonucleotide (ASO) in mice inhibits SCD in the liver and adipose, resulting in increased insulin sensitivity, decreased hepatic fatty acid synthesis, and prevention of HFD-induced obesity and hepatic steatosis." (PMID 38469144, 2024). "Among genes that may regulate basal lipolysis and indirectly, insulin action in fat cells, only CIDEA, PDE3B and receptors for testosterone displayed different expression in men with obesity (higher values) compared with women with obesity." (PMID 38491191, 2024). "All studies investigating cutaneous microvascular reactivity in groups affected by overweight/obesity through iontophoresis with MCh, insulin, and local heating reported non-significant findings." (PMID 39595054, 2024). "Specifically, the neutrophil-to-lymphocyte ratio (NLR) showed a positive correlation with HOMA-IR and serum insulin levels, irrespective of the obesity level in PCOS patients." (PMID 39911236, 2024). "The correlation of HOMA-IR or insulin and asprosin levels were neither negative nor positive, mainly depended on the decreased or increased asprosin levels in subjects with obesity stated in each study." (PMID 38475734, 2024). "An intriguing finding was that resveratrol treatment in women with severe obesity increased insulin action and AMPK phosphorylation without changing other components in the AMPK signaling network, such as SIRT1 and PGC1α." (PMID 38324260, 2024). "Studies have shown that in obesity, adipose tissue, especially visceral adipose tissue (VAT), contributes to whole-body glucose intolerance through dysfunctional adipocytes that exhibit impaired GLUT4-mediated glucose transport and insulin signaling." (PMID 39337290, 2024). "In mouse and human visceral WAT, obesity induces activation of a macrophage-dependent non-neuronal cholinergic system that is capable of exerting anti-inflammatory and insulin-sensitizing effects on white adipocytes." (PMID 38141849, 2024). "In addition, in male albino Wistar rats fed with a HFD, and intervened with GCBE when obesity was established, the extract decreased the body and organ weights, and reduced TC, TG, LDL-C, VLDL, glucose, and insulin levels." (PMID 39065815, 2024). "Moreover, in a mouse model of diet-induced obesity, CXCL14 promotes the conversion of WAT to a more metabolically active state (browning) and improves glucose and insulin regulation." (PMID 39335642, 2024). "One limitation of our assessment of glucose metabolism is that we assessed glucose but not insulin tolerance, which would have provided a more complete understanding of metabolic responses to obesity." (PMID 39347015, 2024).
Obesity (continued). "Taken together, our study demonstrates that exposure to RL promotes obesity in HDF-fed mice, leading to glucose intolerance, which may be due to light-induced changes in appetite hormone and insulin levels regulating appetite gene expression." (PMID 39770951, 2024). "On the other hand, there are studies that demonstrated negative correlations of apelin with HOMA indices and insulin concentrations, while apelin concentrations were lower in subjects with obesity, although the sample size was very small." (PMID 39519480, 2024). "In the present study, resveratrol-induced improvements in insulin action in myotubes from donors with severe obesity occurred in the absence of changes in insulin signaling." (PMID 38324260, 2024). "Regular physical activity enhances insulin sensitivity and improves glycemic control through multiple mechanisms, thereby mitigating the development and progression of insulin resistance-related disorders such as T2DM, obesity, and cardiovascular disease." (PMID 38920999, 2024). "Adolescents with metabolically healthy overweight/obesity (MHO) have a favourable cardio-metabolic status, presenting normal lipid profile, insulin sensitivity and blood pressure, while adolescents with metabolically unhealthy overweight/obesity (MUO) have an unfavourable metabolic profile." (PMID 38166997, 2024). "Recent researches have shown that the obesity paradox is not universal and that a variety of variables such as gender, uric acid levels, and insulin sensitivity influence its existence." (PMID 38846495, 2024). "This discovery aligns with the observation that intermittent energy restriction may effectively reduce obesity-related inflammation (including IL-1β and IFN-γ) and enhance insulin sensitivity compared to continuous energy restriction." (PMID 38622732, 2024). "Facility-dependent differences in insulin response, for example, are not accompanied by differences in high-fat diet-induced obesity." (PMID 39360185, 2024). "Findings from the current study revealed that the serum insulin concentrations and HOMA-IR at different time points of OGTT in women of vitamin D group (obesity) were significantly lower than that in control group (obesity)." (PMID 39014475, 2024). "Between-group comparisons demonstrated significant differences between the groups in terms of obesity indices (body weight, BMI, and PBF), lipid profiles (TG, TC, LDL-C, and HDL-C), FBS and insulin levels, HOMA-IR, and HOMA-B at the end of the study (p < 0.05)." (PMID 39080737, 2024). "Obesity is a majorcausative factor for obstructive sleep apnea, but insulin resistance develops inthese patients irrespective of general adiposity (body mass index)." (PMID 39076340, 2024). "Some studies have observed a substantial enhancement in insulin sensitivity with a LC diet, even in the absence of obesity." (PMID 39000187, 2024). "The fact that circulating insulin levels are decreased by half in OcnBW−/− mice provides a plausible element of explanation for why the obesity characterizing WT OcnBW mice is not observed in mutant mice of these strain." (PMID 38228788, 2024). "Previous studies have shown that obesity can lead to inflammation, and inflammation is attributed to overexpression of Monocyte Chemoattractant Protein-1 (MCP-1), which leads to defective insulin secretion, insulin resistance, and interference with other process of energy homeostasis." (PMID 39165513, 2024). "Meanwhile, in obesity, saturated fatty acids induce the ATM to polarize to an M1 phenotype, producing IL-6, TNF-α, IL-12, and IL-1β, among other inflammatory factors contributing to the impairment of insulin signaling and promoting IR." (PMID 38610754, 2024). "The mechanisms involved between obesity and CVD mainly include insulin resistance, oxidative stress, inflammation, and adipokine dysregulation, which cause maladaptive structural and functional alterations of the heart, particularly left-ventricular remodeling and diastolic dysfunction." (PMID 39065815, 2024).
Obesity (continued). "Obesity, IR, and HA are the most frequent presentations of PCOS; therefore, among the most common treatments are antiandrogenic drugs such as combined oral contraceptives (COCP) and insulin sensitizers like metformin." (PMID 39507182, 2024). "Under normal physiological conditions, insulin can efficiently traverse the blood-brain barrier (BBB) through a receptor-mediated transport mechanism, with transport rates influenced by various factors like obesity and inflammation." (PMID 38425702, 2024). "In line with our study, Sim and colleagues reported that the plasma concentration of insulin did not change after exercise in people with obesity or overweight." (PMID 39263536, 2024). "However, studies in obese animal models and human subjects indicate that obesity and HFD feeding can impair insulin transport across the BBB." (PMID 38678254, 2024). "Children and adolescents with obesity and normal insulin sensitivity do not exhibit similar alterations in glucagon and incretin secretion, highlighting potential for targeted interventions." (PMID 38087928, 2024). "Thus, obesity promotes NLRP3 and macrophage-mediated T-cell activation in adipose tissues, which are also responsible for insulin sensitivity." (PMID 38945951, 2024). "The carbohydrate–insulin model of obesity theorizes that the accumulation of adipose tissue is due not only to a high caloric intake but also to the propensity of carbohydrates to increase insulin secretion and thus stimulate de novo lipogenesis." (PMID 38474774, 2024). "The patient resumed hemodialysis, increased insulin requirements, and reached grade III obesity." (PMID 39606037, 2024). "Furthermore, in subjects with obesity, bariatric surgery was shown to increase the plasma levels of GDF15 and insulin sensitivity, suggesting a possible positive role of GDF15 on insulin activity in humans." (PMID 38668314, 2024). "The kidney is particularly susceptible to lipotoxic damage, which is mediated by factors such as malfunctioning adipose tissue, insulin resistance, elevated plasma nonesterified fatty acids, and obesity." (PMID 38212770, 2024). "The control subgroup without obesity had significantly lower fasting insulin levels than the control subgroup with obesity." (PMID 38276866, 2024). "These factors included obesity (BMI ≥ 30 kg/m2) at the start of the index pregnancy, earlier GDM diagnosis (end of second trimester versus beginning of third trimester), and severe GDM requiring insulin treatment." (PMID 39589852, 2024). "The 5:2 diet for six months was feasible and efficient to reduce markers of insulin secretion and resistance and therefore holds promise as management of overweight/obesity in subjects with and without T2D." (PMID 39273678, 2024). "Indeed, whole-body PTP1B knockout (KO) mice exhibit enhanced insulin sensitivity, elevated phosphorylation of IR and IRS-1, and resistance to high-fat diet (HFD)-induced weight gain and obesity." (PMID 39238503, 2024). "In this regard, the literature, based on numerous independent and diverse observations, highlights a clear role for GIPR activation in the development of obesity, grounding the concept of GIPR antagonism as a potential approach to alleviate insulin resistance and excessive weight gain." (PMID 38861364, 2024). "The combination of aerobic and resistance training significantly reduces body composition and metabolic health in children and adolescents with overweight or obesity, as evidenced by changes in various parameters (BMI, WC, FM, BF%, VO2max, TG, TC, HDL-C, LDL-C, HOMA-IR, FPG, INS)." (PMID 39185113, 2024). "Resveratrol elicited no changes in insulin-stimulated pThr308 in both groups, whereas resveratrol tended to reduce the difference between lean women versus women with severe obesity (P = 0.10)." (PMID 38324260, 2024).
Obesity (continued). "This study indicated that insulin was probably a residual risk factor of CHD but not stroke, and that there was a possible presence of obesity paradox in patients with T2DM on statin therapy." (PMID 38263010, 2024). "Findings also support a positive association of serum lipocalin-2 with other cardiovascular disease risk factors such as abnormal lipids profile or increased fasting glucose and insulin levels, after 12-week supervised HIIT intervention among young men with obesity." (PMID 37238398, 2023). "Among adipokines, chemerin has emerged as a significant predictor of obesity and T2DM, and it may mediate glucose-induced insulin secretion through its receptor." (PMID 37298086, 2023). "The study by Sipe and colleagues observed that a low-GI diet reduced postprandial glucose and insulin secretion in individuals with prediabetes and obesity, but no changes were seen in measures of β-cell function after a 4-week intervention." (PMID 38140319, 2023). "The first observation obtained from this study was the obvious anti-obesity, hypoglycemic, and peripheral insulin-improving effects of XH, which were independent of modulating food intake." (PMID 38231665, 2023). "In addition, due to the sensitizing effect of insulin and preventing weight gain, MTF is also used in the treatment of diseases such as obesity, polycystic ovary syndrome, and type 1 DM." (PMID 37605728, 2023). "In our study, gut microbiota recipient mice from obese donors do not show any leptin or insulin elevation typical from obesity." (PMID 37106463, 2023). "MiR-223 and miR-93 downregulate GLUT4 expression and inhibit insulin-stimulated glucose uptake in adipocytes, suggesting that they may play an important role in other IR-related diseases such as T2DM and obesity." (PMID 36873932, 2023). "At the baseline, the group of people with incident TB were older (64 vs. 57 years), had a lower prevalence of obesity (BMI; 23.6 vs. 24.9 kg/m2), included more men (66.5 vs. 60%), had a higher prevalence of CKD or CVD, and were more likely to be taking insulin treatment or multiple OHAs." (PMID 37041513, 2023). "The authors determined the level of Expression of Leptin (LEP) in Polycystic Ovary Syndrome (PCOS) patients with or without obesity and in GCs treated with insulin." (PMID 37562217, 2023). "Human studies suggest that propionate has overall anti-obesity effects, as it can increase post-prandial GLP-1 and PYY levels, reduce weight gain, intra-abdominal fat, and intrahepatocellular lipid content, and prevent insulin sensitivity issues." (PMID 38132864, 2023). "If all lean subjects were evaluated together, in both sexes proxy measures of obesity, concentrations of insulin, non-HDL-C, CRP, homocysteine, cMSS5, and leukocyte counts showed a direct—and QUICKI, a significant—inverse association with AIP." (PMID 37508640, 2023). "Conversely, lack of CB1Rs or inhibition of CB1Rs improves insulin signaling, thus improving IR and pancreatic beta cell function and reducing hepatic steatosis and obesity." (PMID 36830844, 2023). "The measured parameters of children with obesity, IR, and an early insulin response were similar to those of children with obesity but without IR." (PMID 37599368, 2023). "As for other studies, the method used to estimate insulin clearance has been validated against a clamp-derived method in young individuals with obesity, but it does not distinguish peripheral and hepatic contribution to clearance." (PMID 37834412, 2023). "SFD consumption and obesity development were accompanied by increases in the plasma concentrations of glucose, insulin, and FGF21 in mice of both sexes, regardless of maternal obesity." (PMID 36982684, 2023). "Exposure of L6 muscle cells to palmitate, a saturated FFA, to simulate the in vivo scenario of elevated FFA plasma levels often seen in obesity, dramatically reduced the plasma membrane levels of GLUT4 and insulin-stimulated glucose uptake, indicating insulin resistance." (PMID 36982168, 2023).
Obesity (continued). "Furthermore, significantly higher circulating insulin levels, hs-CRP, and HbA1C, as well as HOMA-IR values, were observed in women with obesity Also, the obese group showed higher levels of creatinine, TC, and LDL-C compared to the normal-weight controls." (PMID 36609306, 2023). "Furthermore, a notable decline in weight increase and a drop in plasma concentrations of leptin, triglycerides, insulin, and glucose were observed in cases of NAFLD induced by fipronil or obesity, in comparison to the control group." (PMID 37958712, 2023). "Overall, these data suggest that high circulating levels of insulin (and/or other adiposity hormones, like leptin) in obesity can lead to striatal InsR insensitivity, independent of the caloric source used to induce obesity." (PMID 36979453, 2023). "In this study, nine non-diabetic insulin-resistant volunteers with obesity, including eight women and one man (ratio of 1:8), were enrolled in the population, with a mean age of 49 ± 7 years (distribution range of 34 to 58 years)." (PMID 37627476, 2023). "The chronic state of obesity triggers negative conditions like hyperglycaemia and T2D, due to the insufficient production of insulin." (PMID 38137918, 2023). "To date, however, no studies exist in humans that have tested if circulating BAIBA levels are different in people with obesity who are normal glucose tolerant (NGT) compared with those with prediabetes (PD) in relation to adiposopathy, insulin sensitivity, or energy metabolism." (PMID 37780967, 2023). "PubMed, Web of Science, and Scopus were searched for original articles, published through October 2022 that included exercise versus control interventions on fasting glucose, insulin, HOMA-IR, and body weight outcomes in children and adolescents with overweight or obesity." (PMID 37635963, 2023). "Insulin resistance is another suggested key factor in the development of T2DM that can be a consequence of obesity-induced inflammation, resulting in a lack of sensitivity toward secreted insulin and elevated blood sugar levels, which are hallmarks of T2DM." (PMID 37113754, 2023). "Regardless of the presence of obesity and its obvious effect on insulin sensitivity, the evidence suggests that women with PCOS exhibit an intrinsic form of IR that is unique to this disorder." (PMID 37371662, 2023). "In CEACAM1 null mice, the absence of CEACAM1 led to an inability to clear insulin, leading to hyperinsulinemia followed by insulin resistance, obesity, and non-alcoholic steatohepatitis." (PMID 36741860, 2023). "Level of insulin is lower than that in other obese models.NZO islets lack the ability to initiate cell-cycle progression and to maintain the survival pathway.More sensitive to high-fat diet-induced obesity." (PMID 36986591, 2023). "At later stages of obesity, a high quantity of endotrophin is produced by the MMP14-induced digestion of COL6α3, which has pro-inflammatory and pro-fibrotic actions, contributing to insulin resistance." (PMID 37445827, 2023). "Similar results were obtained in obese Beagle dogs, in which supplementation with green tea extract increased PPARꭤ, GLUT4, and LPL expression, followed by insulin sensitivity and lipid profile improvement, suggesting that EGCG is able to reverse obesity-related metabolic disturbances." (PMID 37375898, 2023). "In addition, recently, Single nucleotide polymorphisms (SNPs) related to lipid metabolism or insulin or glucose metabolism were observed in the MUHO or MUHNW groups, suggesting that they may be associated with CVD outcome at the gene level and the phenotype of obesity or MUH23,24." (PMID 36635350, 2023). "It is well known that blood levels of triglycerides, cholesterol, glucose, and insulin greatly differ between children with and without obesity, rendering these parameters good biomarkers for metabolic derangement." (PMID 37190014, 2023).